CHMP1A (charged multivesicular body protein 1A)
Description:
Probable peripherally associated component of the endosomal sorting required for transport complex III (ESCRT-III) which is involved in multivesicular bodies (MVBs) formation and sorting of endosomal cargo proteins into MVBs. MVBs contain intraluminal vesicles (ILVs) that are generated by invagination and scission from the limiting membrane of the endosome and mostly are delivered to lysosomes enabling degradation of membrane proteins, such as stimulated growth factor receptors, lysosomal enzymes and lipids. The MVB pathway appears to require the sequential function of ESCRT-O, -I,-II and -III complexes. ESCRT-III proteins mostly dissociate from the invaginating membrane before the ILV is released. The ESCRT machinery also functions in topologically equivalent membrane fission events, such as the terminal stages of cytokinesis and the budding of enveloped viruses (HIV-1 and other lentiviruses). ESCRT-III proteins are believed to mediate the necessary vesicle extrusion and/or membrane fission activities, possibly in conjunction with the AAA ATPase VPS4. Involved in cytokinesis. Involved in recruiting VPS4A and/or VPS4B to the midbody of dividing cells. May also be involved in chromosome condensation. Targets the Polycomb group (PcG) protein BMI1/PCGF4 to regions of condensed chromatin. May play a role in stable cell cycle progression and in PcG gene silencing.
Synonyms: Vps46-1; CHMP1; KIAA0047; PCOLN3; PRSM1; Vps46A; PCH8
Tractability: Small molecule: a structure with a bound ligand is known. Antibody: its Gene Ontology location is reachable by antibodies, with high confidence; UniProt places it where antibodies can reach, with medium confidence. PROTAC: ubiquitination databases record sites on it; its protein half-life has been measured.
Gene: Protein-coding gene on chromosome 16 (89,640,816 to 89,657,738, reverse strand). Ensembl gene ENSG00000131165.
Subcellular location: Cytoplasm; Endosome membrane; Nucleus matrix
Subcellular location (Human Protein Atlas): Centrosome; Cytosol; Nucleoplasm
Pathways (Reactome):
Disease: HCMV Late Events
Gene Ontology:
Molecular function: identical protein binding; protein binding; protein domain specific binding; protein homodimerization activity; metallopeptidase activity; zinc ion binding
Biological process: autophagosome maturation; autophagy; cell division; late endosome to lysosome transport; midbody abscission; mitotic chromosome condensation; mitotic metaphase chromosome alignment; multivesicular body sorting pathway; negative regulation of gene expression; nuclear membrane reassembly; nucleus organization; plasma membrane repair; regulation of centrosome duplication; regulation of mitotic spindle assembly; ubiquitin-dependent protein catabolic process via the multivesicular body sorting pathway; vesicle-mediated transport; viral budding from plasma membrane; viral budding via host ESCRT complex; ESCRT III complex disassembly; late endosome to vacuole transport; membrane fission; multivesicular body assembly; multivesicular body-lysosome fusion; vesicle fusion with vacuole; vacuolar transport
Cellular component: amphisome membrane; autophagosome membrane; condensed nuclear chromosome; cytosol; early endosome; endomembrane system; extracellular exosome; kinetochore; kinetochore microtubule; lysosomal membrane; microtubule organizing center; midbody; multivesicular body membrane; nuclear matrix; nuclear pore; nucleoplasm; plasma membrane; ESCRT III complex; cytoplasm; endosome membrane
Genetic constraint (gnomAD): Loss-of-function variants: 17 observed, 24.41 expected, observed/expected ratio (o/e) 0.7, 90% interval 0.48 to 1.04. The upper end of that interval is the gene's LOEUF score, 1.04, which puts it in group 4 of 6, group 1 being the genes least tolerant of losing a copy. Missense variants: 275 observed, 263.26 expected, observed/expected ratio (o/e) 1.04, 90% interval 0.95 to 1.15. Synonymous variants: 131 observed, 105.59 expected, observed/expected ratio (o/e) 1.24, 90% interval 1.08 to 1.43.
Homologues: Orthologues: guinea pig CHMP1A (98% identical), dog CHMP1A (97% identical), mouse Chmp1a (97% identical), pig CHMP1A (97% identical), rabbit CHMP1A (95% identical), rat Chmp1a (94% identical), tropical clawed frog chmp1a (90% identical), zebrafish chmp1a (87% identical). Paralogues in human: CHMP1B (56% identical), CHMP2A (25% identical), CHMP2B (16% identical), CHMP3 (16% identical).